MXRA8 (matrix remodeling associated 8)
Description:
Transmembrane protein which can modulate activity of various signaling pathways, probably via binding to integrin ITGAV:ITGB3. Mediates heterophilic cell-cell interactions in vitro (By similarity). Inhibits osteoclastogenesis downstream of TNFSF11/RANKL and CSF1, where it may function by attenuating signaling via integrin ITGB3 and MAP kinase p38 (By similarity). Plays a role in cartilage formation where it promotes proliferation and maturation of growth plate chondrocytes (By similarity). Stimulates formation of primary cilia in chondrocytes (By similarity). Enhances expression of genes involved in the hedgehog signaling pathway in chondrocytes, including the hedgehog signaling molecule IHH; may also promote signaling via the PTHLH/PTHrP pathway (By similarity). Plays a role in angiogenesis where it suppresses migration of endothelial cells and also promotes their apoptosis. Inhibits VEGF-induced activation of AKT and p38 MAP kinase in endothelial cells. Also inhibits VTN (vitronectin)-mediated integrin ITGAV:ITGB3 signaling and activation of PTK2/FAK. May play a role in the maturation and maintenance of the blood-brain barrier (By similarity). (Microbial infection) Contributes to arthritogenic alphavirus pathogenesis and acts as a receptor for these viruses.
Synonyms: DKFZp586E2023; ASP3
Tractability: Antibody: UniProt places it where antibodies can reach, with high confidence; UniProt predicts a signal peptide or a membrane-spanning region; its Gene Ontology location is reachable by antibodies, with medium confidence. PROTAC: ubiquitination databases record sites on it.
Gene: Protein-coding gene on chromosome 1 (1,352,689 to 1,361,777, reverse strand). Ensembl gene ENSG00000162576.
Subcellular location: Cell membrane; Cell junction, tight junction; Cytoplasm; Cell projection, cilium membrane; Nucleus
Subcellular location (Human Protein Atlas): Nucleoli
Pathways (Reactome):
Metabolism of proteins: Post-translational protein phosphorylation; Regulation of Insulin-like Growth Factor (IGF) transport and uptake by Insulin-like Growth Factor Binding Proteins (IGFBPs)
Gene Ontology:
Molecular function: protein binding
Biological process: cell differentiation; establishment of glial blood-brain barrier; cell adhesion
Cellular component: extracellular exosome; nucleus; plasma membrane; cell surface; cytoplasm; endoplasmic reticulum lumen; bicellular tight junction; ciliary membrane; membrane
Genetic constraint (gnomAD): Loss-of-function variants: 44 observed, 35.1 expected, observed/expected ratio (o/e) 1.25, 90% interval 0.98 to 1.61. The synonymous counts are far from expectation, so gnomAD's model fits this gene poorly and the ratio says little. Missense variants: 765 observed, 556.05 expected, observed/expected ratio (o/e) 1.38, 90% interval 1.3 to 1.46. Synonymous variants: 369 observed, 246.46 expected, observed/expected ratio (o/e) 1.5, 90% interval 1.37 to 1.63.
Homologues: Orthologues: macaque MXRA8 (98% identical), chimpanzee MXRA8 (91% identical), dog MXRA8 (84% identical), rat Mxra8 (79% identical), mouse Mxra8 (79% identical), guinea pig MXRA8 (67% identical), pig MXRA8 (65% identical), tropical clawed frog mxra8 (52% identical), zebrafish mxra8a (46% identical), zebrafish mxra8b (40% identical). Paralogues in human: CXADR (16% identical), CLMP (16% identical), ESAM (14% identical), VSIG2 (14% identical), IGSF11 (14% identical), JAM3 (14% identical), JAM2 (13% identical), VSIG8 (13% identical), F11R (12% identical), VSIG1 (12% identical), GPA33 (12% identical), VSTM2B (10% identical), and 2 more.
Diseases named in the same sentence as MXRA8 in open-access papers:
MXRA8 is named in the same sentence as 34 diseases in open-access papers, as found by Europe PMC text mining. Sharing a sentence is not in itself a finding about the gene and the disease. The quoted sentences say what the papers report.
glioma (9 papers, 2022 to 2024). A benign or malignant brain and spinal cord tumor that arises from glial cells (astrocytes, oligodendrocytes, ependymal cells). "MXRA8 has also been associated with reduced survival in renal clear cell carcinoma, and MXRA8 promotes glioma by regulating ferroptosis." (PMID 37762032, 2023). "Downregulation of matrix-remodeling-associated protein 8 (MXRA8) increases the intracellular levels of lipid peroxidation in glioma cells, leads to NCOA4 upregulation and inhibits ferritin heavy chain 1 (FTH1)." (PMID 36937406, 2023). "The expression of MXRA8 was significantly higher in glioma compared with normal brain tissue, and increased expression of MXRA8 was associated with unfavorable survivals." (PMID 35281049, 2022). "Similarly, matrix remodeling-associated protein 8 (MXRA8) was also identified as a prognostic indicator for glioma." (PMID 38961066, 2024). "Matrix remodeling-associated protein 8 (MXRA8) was found to be overexpressed in glioma cells, and it could be involved in the infiltration of M2 macrophages, contributing to immune response to glioma by regulating ferroptosis." (PMID 38159261, 2023). "Furthermore, our studies revealed that MXRA8 expression was positively associated with levels of these immunoinhibitory factors involved in microenvironment of glioma." (PMID 35281049, 2022). "Accordingly, MXRA8 facilitates glioma progression and critically affects glioma ferroptosis and the immune microenvironment." (PMID 36937406, 2023). "Our study uncovers the essential roles of MXRA8 in glioma progression and highlights the importance of MXRA8 in regulating ferroptosis and immune microenvironments." (PMID 35281049, 2022). "We identified that Matrix remodeling-associated protein 8 (MXRA8) is highly expressed in glioma sample and is associated with poor prognosis of glioma." (PMID 35281049, 2022). "We also detected the expression of MXRA8 in different grades of glioma from two CGGA datasets (RNAseq_325 and RNAseq_693) and observed that MXRA8 was obviously elevated in high-grade glioma." (PMID 35281049, 2022). "In order to explore the biological functions of MXRA8 in glioma, we performed the coexpression pattern of MXRA8 screened from the TCGA-GBMLGG cohort by the LinkFinder module of LinkedOmics." (PMID 35281049, 2022). "Natural killer cells (NK), macrophages, and neutrophils were found to be positively correlated with MXRA8 in glioma." (PMID 35281049, 2022). "GSE59612 and GSE147352 datasets respectively showed that expression of MXRA8 was significantly higher in gliomas than those in normal tissues." (PMID 35281049, 2022). "To further validate the role of MXRA8 in the malignant progression of glioma, we analyzed its expression levels in the TCGA datasets from the GEPIA2.0 and UALCAN platform, respectively." (PMID 35281049, 2022). "One study co-cultured glioma cell with M2 macrophages and found that MXRA8 knockdown in glioma cells attenuated the infiltration of M2 macrophages, while the addition of Fer-1 restored the infiltration of M2 macrophages." (PMID 36185243, 2022). "To further examine the biological effect of MXRA8 in glioma, we knocked down MXRA8 with two small interfering RNAs in T98G and U251 cell lines." (PMID 35281049, 2022). "Collectively, these results suggest that downregulation of MXRA8 improved the sensitivity of glioma to TMZ." (PMID 35281049, 2022). "MXRA8 knockdown in glioma cells attenuates M2 macrophage infiltration." (PMID 36937406, 2023). "Our data suggest that MXRA8 might act as a potential prognostic marker for glioma involving ferroptosis and immunity mediation." (PMID 35281049, 2022). "Although these results demonstrated that MXRA8 was universally expressed on multiple tumor types, such as breast cancer, kidney cancer, and glioma, we found that the level of MXRA8 expression varied greatly among patients even within the same histological type." (PMID 35393389, 2022). "The demographic characteristics of MXRA8 expression in glioma." (PMID 35281049, 2022).
glioma (continued). "Taken together, these data indicated that knockdown of MXRA8 could suppress cell survival and enable ferroptosis in glioma cells." (PMID 35281049, 2022). "MXRA8 expression levels were higher in glioma than those in normal specimens." (PMID 35281049, 2022). "The lower expression of MXRA8 was correlated with better prognosis of gliomas." (PMID 35281049, 2022). "Furthermore, we demonstrated that knockdown of MXRA8 inhibited cell proliferations in vitro and contributed to increasing sensitivity of glioma cells to TMZ." (PMID 35281049, 2022). "Additionally, immune infiltration score in the TCGA glioma datasets showed that patients with high immune infiltration had a tendency with upregulation of MXRA8, which couples with worse OS." (PMID 35281049, 2022). "Also, the protein expression level of NCOA4 was increased in MXRA8 knockdown glioma cells, while FTH1 was reduced." (PMID 35281049, 2022). "Our present study firstly demonstrated that knockdown of MXRA8 could inhibit M2 macrophage migration to glioma cells through regulation of ferroptosis." (PMID 35281049, 2022). "The co-cultured models of glioma cells and M2 macrophages showed MXRA8 knockdown glioma cells alleviated the infiltration of M2 macrophage, while the reduced M2 macrophage infiltration generated by MXRA8 could be rescued by Fer-1 treatment." (PMID 35281049, 2022). "In addition, the promoting effect of MXRA8 was further demonstrated on 769-P (kidney carcinoma) and U-87MG (glioma) cell models." (PMID 35393389, 2022). "Furthermore, in vitro analysis showed that knockdown of MXRA8 inhibited the cell viability in T98G and U251 cells and increased the sensitivity of glioma cells to temozolomide." (PMID 35281049, 2022). "Therefore, we further explored the role of MXRA8 in the immune microenvironment of glioma." (PMID 35281049, 2022). "Therefore, our findings suggest that MXRA8 could be a promising prognostic biomarker in patients with glioma." (PMID 35281049, 2022). "Interestingly, a receptor for multiple arthritogenic alphaviruses, MXRA8, which showed the highest correlation with ferroptosis may be involved in glioma progression and prognosis." (PMID 35281049, 2022). "Knockdown of MXRA8 increased the protein expression of NCOA4 and decreased the levels of FTH1, resulting in ferroptosis of glioma cells." (PMID 38961066, 2024). "Previous studies have reported the involvement of PDIA4, MXRA8, PDLIM4, C9orf64, and GZMB in glioma patients’ poor prognosis through bioinformatics analysis." (PMID 38159261, 2023). "However, the underlying functions of MXRA8 in gliomas have not been elucidated." (PMID 35281049, 2022). "Therefore, MXRA8 may serve as a novel prognostic marker and therapeutic target for glioma." (PMID 35281049, 2022). "In our studies, we firstly found that downregulation of MXRA8 could induce ferroptosis by elevating the Fe2+ and MDA levels in glioma cells." (PMID 35281049, 2022). "Likewise, our study also demonstrated that inhibition of MXRA8 increased the protein expression of NCOA4 and decreased FTH1 protein levels in glioma cells." (PMID 35281049, 2022). "Moreover, in this study, we also observed that one glioma and 23 liver tumor patients were negative for MXRA8 staining by RNA-scope or IHC, and the tumor MXRA8 expression in brain, kidney, breast, and liver tumor patients varied wildly." (PMID 35393389, 2022).
breast carcinoma (5 papers, 2022 to 2025). "The loss of MXRA8 also led to a decrease in the expression of genes associated with breast cancer, including ADAMTS1, TIE1, and BMP2." (PMID 37762032, 2023). "While MXRA8 has been associated with reduced survival in patients with colorectal and renal clear cell cancers, the role of MXRA8 in breast cancer remains largely unexplored." (PMID 37762032, 2023). "Our findings indicate that the loss of MXRA8 expression suppresses mammary tumor onset and metastasis." (PMID 37762032, 2023). "These mice were used as a pilot study to determine if the loss of MXRA8 impacted mammary tumor development in vivo." (PMID 37762032, 2023). "MXRA8 was further investigated as elevated levels of MXRA8 were associated with reduced distant metastasis free survival in breast cancer patients." (PMID 35456497, 2022). "Only elevated MXRA8 was significantly associated with a decrease in distant metastasis free survival in basal-like breast cancer patients." (PMID 35456497, 2022). "Our work also suggests that MXRA8 is associated with breast cancer metastasis, as lung metastases expressed high levels of MXRA8 and high MXRA8 was associated with poor distant metastasis free survival in patients with basal-like breast cancer." (PMID 35456497, 2022). "In summary, the loss of MXRA8 reduced breast cancer initiation and metastasis in human triple-negative breast cancer cells, and high levels of MXRA8 protein were associated with more aggressive breast cancer subtypes." (PMID 37762032, 2023). "It is also interesting to note that SUZ12 ChEA was also the top ENCODE and ChEA pathway in MDA-231c141 tumors, the tumors where we identified MXRA8′s potential role in breast cancer." (PMID 37762032, 2023). "Further support demonstrating that MXRA8 plays a role in breast cancer stems from our work with murine mammary tumor cell lines." (PMID 35456497, 2022). "This is the first study to implicate MXRA8 in human breast cancer, and our data suggests that miR-200s inhibit growth and metastasis of claudin-low mammary tumor cells in vivo through downregulating MXRA8 expression." (PMID 35456497, 2022). "Quantitative RT-PCR and Western blotting confirmed that MXRA8 expression was significantly higher in mammary tumors induced by MDA-231EV cells compared to those induced by MDA-231c141 cells." (PMID 35456497, 2022). "The reduced levels of MXRA8 in the mammary tumors induced by MDA-231c141 cells implicate this gene in regulating mammary tumor growth and metastasis." (PMID 35456497, 2022). "Similarly, human breast cancer Hs 578T cells retained sensitivity to OVM infection even when MXRA8 is knocked out." (PMID 41053536, 2025). "Moreover, we found higher levels of MXRA8 protein in patient samples from aggressive breast cancer subtypes (TNBC and HER2+) compared to the less aggressive, ER+ subtype." (PMID 37762032, 2023). "Therefore, it is possible that increased miR-200c/141 levels reduce MXRA8 expression which in turn decreases the expression of breast cancer progression genes like ADAMTS1 and BMP2 potentially through increasing histone methylation." (PMID 37762032, 2023). "However, additional studies are required to further evaluate how MXRA8 can influence breast cancer gene expression." (PMID 37762032, 2023). "Moreover, breast cancers from patients with aggressive subtypes (i.e., TNBC and HER2+) expressed higher levels of MXRA8 protein in primary tumors and metastatic lesions compared to less aggressive, ER+ breast cancers." (PMID 37762032, 2023). "Therefore, the aim of this research was to determine the role of MXRA8 in breast cancer by knocking out MXRA8 in the human triple-negative breast cancer cell line MDA-MB-231." (PMID 37762032, 2023). "The characterization of MXRA8 in most cancers, including breast cancer, is limited." (PMID 37762032, 2023). "Thus, our study is the first to manipulate MXRA8 expression and determine its function in breast cancer." (PMID 37762032, 2023).
breast carcinoma (continued). "Transcriptome profiling of MDA-231EV and MDA-231c141 tumors revealed a number of genes regulated by the miR-200c/141 cluster that could influence mammary tumor growth and metastasis including MXRA8." (PMID 35456497, 2022). "Therefore, our work demonstrates for the first time that MXRA8 is elevated in fast growing mammary tumors with a high metastatic potential." (PMID 35456497, 2022). "Moreover, this is the first study implicating MXRA8 as a potential regulator of mammary tumor growth and metastasis." (PMID 35456497, 2022). "Therefore, the loss of MXRA8 may influence intracellular signaling pathways that in turn alter the expression of genes like ADAMTS1, TIE1, and BMP2 that regulate breast cancer metastasis." (PMID 37762032, 2023). "Exactly how MXRA8 influences mammary tumor onset and metastasis remains unclear." (PMID 37762032, 2023). "MXRA8 staining of a human breast cancer tissue array revealed higher levels of MXRA8 in primary tumors and metastases of aggressive tumor subtypes (TNBC and HER2+) compared to less aggressive, ER+ breast cancers." (PMID 37762032, 2023). "While MXRA8 has been associated with esophageal, kidney, gingivobuccal cancer, there are no publications on MXRA8 in breast cancer." (PMID 35456497, 2022). "According to the Cancer Cell Line Encyclopedia (CCLE) database, MXRA8 is highly expressed on HepG2 (hepatocellular carcinoma) and Hs578T (breast carcinoma) cells, but not detectable on HeLa (cervical carcinoma) or HT29 (colorectal carcinoma) cells." (PMID 35393389, 2022).
virus infection (5 papers, 2020 to 2024). "The matrix-remodelling-associated protein 8 (MXRA8) is known as a receptor of viral infection, but its role in cell adhesion and angiogenesis has been gradually discovered in recent years." (PMID 32450814, 2020). "Notably, expression of cellular factors at levels insufficient for protein detection can nevertheless affect virus infection, as demonstrated for the alphavirus receptor, MXRA8, and the interferon stimulated gene, LY6E." (PMID 38712102, 2024).
colorectal cancer (3 papers, 2022 to 2023). A primary or metastatic malignant neoplasm that affects the colon or rectum. "In colorectal cancer, MXRA8 was associated with a poor prognosis and correlated with metastasis, recurrence, and an immunosuppressive tumor microenvironment." (PMID 37762032, 2023). "Moreover, our result showed that MXRA8 overexpression brought limited benefit in the oncolysis of OVM to LoVo cell line (colorectal carcinoma) which is resistant to OVM." (PMID 35393389, 2022).
renal clear cell carcinoma (3 papers, 2022 to 2023). "High MXRA8 expression is associated with poorer overall survival in clear cell renal cell carcinoma, but the potential function of MXRA8 in CRC has not been elucidated." (PMID 36703779, 2022).
breast tumor (2 papers, 2022). "Moreover, to further elucidate the expression of MXRA8 in liver and breast tumors, immunohistochemistry (IHC) was performed on tumor tissue microarrays and normal tissues." (PMID 35393389, 2022).
esophageal cancer (2 papers, 2020 to 2022). A primary or metastatic malignant neoplasm involving the esophagus. "The function of MXRA8 in cancer development and progression has not been addressed, but it has been reported to be highly expressed in thyroid cancer, kidney cancer, esophageal cancer, and pancreatic cancer, Therefore, this study is the first report on the high expression of MXRA8 in CRC." (PMID 36703779, 2022).
thyroid cancer (2 papers, 2022). "Moreover, MXRA8 was significantly upregulated in head and neck squamous cell carcinoma (HNSC), lung adenocarcinoma (LUAD), kidney renal clear cell carcinoma (KIRC) and thyroid carcinoma (THCA) tissues compared with the corresponding normal tissues as evaluated by a paired t-test." (PMID 35393389, 2022).
adenoma (1 paper, 2024). A neoplasm arising from the epithelium. "Top over-represented EV proteins from the adenoma ZMTH3 were mainly related to immune response (ISG15, BST2, IFI44), while top under-represented proteins identified in the adenoma ZMTH3 EVs were associated with migratory and adhesion activity (MXRA8, TNN, SERPINB8), similar to the WCLs." (PMID 39462388, 2024).
colon tumor (1 paper, 2022). "Therefore, a “dual-biomarker system” including the expression of MXRA8 and the deficiency of ZAP is developed here, which can superiorly correlate with the efficacy of OVM in breast, liver, cervix and colon tumor cells as well as liver and kidney surgical cancer explants." (PMID 35393389, 2022).